DICER1 (dicer 1, ribonuclease III)
Diseases named in the same sentence as DICER1 in open-access papers (continued):
Sharing a sentence is not in itself a finding about the gene and the disease.
ovarian carcinoma (35 papers, 2012 to 2025). A malignant neoplasm originating from the surface ovarian epithelium. "In a recent report, a DICER1 mutation carrier was diagnosed with a microprolactinoma and papillary thyroid cancer with multinodular goiter; she had a daughter who died of ovarian cancer." (PMID 32714280, 2020). "For instance, a pattern of down-regulation of DICER1 is associated with poor prognosis in skin, lung, breast, and ovarian cancers, among other cancers." (PMID 26147304, 2015). "Some studies showed that lower levels of DICER1 mRNA expression were associated with the development of lung cancer, colon cancer, and ovarian cancer." (PMID 26688807, 2015). "In ovarian cancer patients, low DICER1 gene expression was significantly associated with advanced tumor stage, poor response to chemotherapy and reduced disease-free survival." (PMID 26087193, 2015). "Low Dicer1 expression is significantly associated with poor prognosis in ovarian cancer and lung adenocarcinoma." (PMID 24223844, 2013). "These investigators found similar mutations in DICER1 only rarely in other solid human tumors, such as endometrial and ovarian cancers." (PMID 23641362, 2013). "In addition to these genes, a high risk for ovarian cancer is associated with mutations in the DICER1, VHL, PTCH1, SUFU, SMARCB1, and SMARCA4 genes." (PMID 37685988, 2023). "Consistently, genetic variants of DICER1 have been found to modulate the risk of gastric cancer, endocrine tumors, ovarian cancer, testicular germ-cell tumors, and neurofibromatosis, and have been found to be associated with head and neck cancer recurrence and ovarian cancer prognosis." (PMID 36672288, 2023). "Low expression of DICER1 is associated with advanced stages and reduced survival in human ovarian cancer, suggesting that DICER1 may act as a potential tumor suppressor." (PMID 32497036, 2020). "Somatic heterozygous mutations in DICER1 are present in 29% of non-epithelial ovarian cancers, including Sertoli-Leydig cell tumors (60%, the majority harboring a E1705K or D1709N hotspot mutation), juvenile GCTs (7%), yolk sac tumors (13%) and mature teratomas (12%)." (PMID 32455687, 2020). "Modification in tumor suppressor DICER1 was liable for the pathogenesis of ovarian cancers, but mutation in this gene may be diagnosed with the growth of GBM." (PMID 31137733, 2019). "Moreover, low Dicer1 expression level was reported and shown to be associated with poor prognostic in a variety of tumors such as lung, breast and ovarian cancers, among others." (PMID 30542509, 2018). "Yet the role of DICER1 loss in ovarian cancer remains to be clarified." (PMID 30424539, 2018). "Low expression of DICER1 is associated with advanced stages and reduced survival in human ovarian cancer (HGSC), suggesting that DICER1 may function as a tumor suppressor." (PMID 30424539, 2018). "In addition, low Drosha or Dicer1 expression levels were associated with advanced tumor stage and poor clinical outcome in patients with ovarian cancer." (PMID 26834703, 2015). "It will also likely be important to recognize the impact of DICER1 mutations in pediatric ovarian cancers could be much more complex than a simple gain or loss of function." (PMID 23641362, 2013). "Mutations in DICER1 have been implicated in inherited syndromes of pediatric ovarian cancer." (PMID 23641362, 2013). "For example, multiple mechanisms could conceivably lead to altered DICER1 expression or function in pediatric ovarian cancers in addition to recently identified mutations." (PMID 23641362, 2013). "It has been shown that gene sets related to RNase III DROSHA and DICER1 were decreased in ovarian cancer." (PMID 33371881, 2020). "Similar to the study of Dicer1 hotspot mutations in endometrial cancer, further studies of the potential role of Dicer1 dysregulations in affecting stromal cells in fallopian tube will provide insights into this potential route of ovarian cancer development." (PMID 27602775, 2016).
ovarian carcinoma (continued). "Despite the excitement generated by the recent discovery of FOXL2 and DICER1 as key tumor suppressors in pediatric ovarian cancers, there is still much to be understood regarding the mechanisms by which these events lead to cancer." (PMID 23641362, 2013). "For example, work examining transcriptional profiles generated for epithelial ovarian cancers by the Cancer Genome Atlas consortium (TCGA) has been unable to confirm that levels of DICER1 transcript are decreased in epithelial ovarian cancers." (PMID 23641362, 2013). "For example, miR-34a could improve cisplatin sensitivity in non-small cell lung carcinoma and miR-98-5p regulated Dicer1 axis and mediated cisplatin resistance in ovarian cancer." (PMID 35027053, 2022). "A decreased expression of Dicer1 and Drosha has been reported in lung and ovarian cancers." (PMID 26834703, 2015). "Several of the DICER1 mutations observed in pediatric ovarian cancers have been shown to disrupt rather than suppress normal patterns of miRNA expression." (PMID 23641362, 2013). "Yet the functional role of DICER1 in ovarian cancer remains unclear." (PMID 32497036, 2020). "In addition, differential expression of DICER1, AGO3, and AGO4 was reported in the estrogen-dependent development of the chicken female reproductive tract and hen’s ovarian cancer, suggesting that the sex-steroid hormones play an essential role in the biosynthesis of miRNAs." (PMID 33477993, 2021).
Wilms tumor (33 papers, 2013 to 2025). An embryonal neoplasm characterized by the presence of epithelial, mesenchymal, and blastema components. "Only one patient with CPAM type 1 developed malignancy in a different site from the pulmonary one (Wilms’ tumor), and genetic analysis revealed the presence of DICER1 gene mutation." (PMID 40069796, 2025). "Only one patient with CPAM developed Wilms’ tumor after 2 years of follow-up, but genetic analysis revealed the presence of a DICER1 gene mutation." (PMID 40069796, 2025). "The commonly known Wilms tumor, which usually has an onset before 2 years of age, can also manifest in association with DICER1 mutations." (PMID 38254836, 2024). "Mutational analysis has shown that DROSHA and DICER1 mutations, commonly found in Wilms tumors, impair miRNA processing." (PMID 39473825, 2024). "DICER1-syndrome has been linked to pleuropulmonary blastomas, Wilms’ tumor, follicular nodular disease, thyroid cancer, and other neoplasias." (PMID 38607000, 2024). "This phenotype added to nephroblastoma has been identified as Glow syndrome with somatic DICER1 mutations." (PMID 37509342, 2023). "Whole genome sequencing, exome sequencing, Sanger sequencing, digital PCR and a review of Wilms tumours with DICER1 RNase III domain mutations were performed." (PMID 33208384, 2022). "A DICER1-related syndrome with the acronym GLOW (global developmental-delay lung cysts-overgrowth-Wilms tumor) is caused by mosaic missense hotspot mutations in DICER1 affecting the RNase IIIb domain." (PMID 35163487, 2022). "Recently, a syndrome with the acronym GLOW (Global developmental delay, Lung cysts, Overgrowth, Wilms tumour) was described in two children with mosaic missense mutations in hotspot residues of the DICER1 RNase IIIb domain." (PMID 33208384, 2022). "It is intriguing that DICER1 mutations (both germline and somatic) have also been identified in solid Wilms tumor cases and the co-occurrence of CN and a Wilms tumor has been reported twice." (PMID 33673661, 2021). "Cystic nephroma was often related to DICER1-mutations and second tumors, whereas cystic partially differentiated nephroblastoma was related to somatic hyperdiploidy, although testing was rare." (PMID 33673661, 2021). "Given the rarity of Wilms tumors in DICER1 pathogenic variant carriers, we adjusted the age and interval at which renal surveillance should be performed to the available data for CN which primarily affects children younger than 5 years of age." (PMID 34170462, 2021). "In the modest‐sized TARGET (pediatric) germline data available, we observed nonhotspot missense (LP) DICER1 variation in one child with a neuroblastoma (one child with Wilms tumor also harbored a DICER1 Likely Pathogenic variant)." (PMID 30672147, 2019). "Furthermore, mutations in miRNA processing enzymes DICER1 or DROSHA are linked with Wilms tumor, indicating the crucial role of miRNAs in the differentiation of mesenchymal stem cells during nephrogenesis and the development of Wilms tumors." (PMID 37345170, 2023). "The pathologic-anatomic diagnosis of the lesion in the middle lobe was initially Wilms tumour metastasis, but following the identification of the pathogenic germline DICER1 variant, pathology review determined that the correct diagnosis was well-differentiated fetal adenocarcinoma." (PMID 33208384, 2022). "However, there are also tumors such as Wilms tumor or pineoblastoma that recurrently have mutations leading to a complete loss of function of DICER1 or that have mutations in other members of the miRNA processing pathway such as mutations in DROSHA and DGCR8." (PMID 32601913, 2020). "Additionally, DICER1 mutations are observed in Wilms tumors as described in the next paragraph." (PMID 37179717, 2023). "Conversely, neoplasms like TFND and DTC in adults, juvenile intestinal polyps, and Wilms tumor have low specificity for germline DICER1 alteration." (PMID 38254836, 2024).
Wilms tumor (continued). "In Wilms’ tumors and pineoblastoma, somatic mutations in miRNA biogenesis genes (DROSHA, DGCR8, DICER1) or in genes involved in the degradation of miRNA (DIS3L2) have also been reported." (PMID 38607000, 2024). "Among the miRNA-processing genes, mutations in DROSHA, DGCR8, DICER1, TARBP2, and XPO5 (encodes exportin 5) have been reported in treatment-naive and neoadjuvant chemotherapy-treated Wilms tumors." (PMID 35531954, 2022). "Moreover, mutations in typical Wilms tumour genes were identified, such as WT1, DIS3L2, WTX, CTNNB1 and the miRNA-processing genes DROSHA, DGCR8 and DICER1." (PMID 32161258, 2020). "Biallelic DICER1 variation is already known to account for a small percentage of Wilms tumors." (PMID 30672147, 2019). "Patients with PPB often have mutations in the DICER1 gene.Early testing for this gene can assist in clarifying the diagnosis.In approximately 10% of cases, PPB may coexist with multilocular cystic nephroma and occasionally with nephroblastoma." (PMID 40046857, 2025). "Ten percent of cases are due to somatic mosaicism for DICER1 variants, which has been associated with earlier disease onset, more DICER1-associated tumors, and a distinctive presentation known as GLOW syndrome (global developmental delay, lung cysts, overgrowth, and Wilms tumor)." (PMID 38067388, 2023). "With exception of hotspot mutations found in DICER1, we found only a few mutations in other miRNA biogenesis genes, i.e. DROSHA, DGCR8 and XPO5, which have been recently observed in different childhood cancers associated with DICER1 syndrome and in Wilms' tumor." (PMID 33406242, 2021). "CN is one of the most common DICER1-associated tumors (estimated cumulative incidence among carriers of a germline DICER1 pathogenic variant [index and non-index case patients] is ~ 7% by the age of 6 years), whereas malignant diseases as Wilms tumors and anaplastic sarcoma are very rare." (PMID 34170462, 2021). "Compared with the other Wilms tumour organoid lines and normal kidney-derived organoids, WT003T showed markedly reduced DICER1 gene expression." (PMID 32161258, 2020). "Germline DICER1 mutations are also associated with non-neoplastic conditions, including macrocephaly, retinal abnormalities, renal anomalies, dental perturbations, and GLOW syndrome (global developmental delay, lung cysts, overgrowth and Wilms’ tumor)." (PMID 36902703, 2023). "It remains unclear why impaired DICER1 function in Wilms tumors results in persistent and aberrant nephrogenesis, unlike loss of Dicer1 in mouse nephron progenitors, which causes increased apoptosis and a premature cessation of nephrogenesis." (PMID 35531954, 2022). "However, if DICER 1 anomalies have been reported in patients with Wilms tumor (WT), to date, no cases of PPB, WT, and DICER1 mutations have been reported in the same patient." (PMID 30097050, 2018).
Cystic Nephroma (30 papers, 2013 to 2026). A benign encapsulated neoplasm of the kidney, characterized by the presence of cysts separated by septa. "The DICER1 gene mutation increases the risk for other hereditary neoplasms, including cystic nephroma, pituitary blastoma, embryonal rhabdomyosarcomas, ovarian sex cord‐stromal tumors, and other tumors." (PMID 40948701, 2025). "Mutations in this complex, including in TARBP2, lead to Dicer1 Syndrome which includes multiple rare malignancies including cystic nephromas and Sertoli-Leydig cell tumors." (PMID 39639036, 2024). "Remarkably, cystic nephroma, another childhood renal tumour composed of large cysts, has been previously linked to DICER1 mutations." (PMID 32161258, 2020). "A recent study of a patient with a cystic nephroma diagnosed as a multicystic left renal tumor was diagnosed with germline and somatic mutations in the DICER1 gene." (PMID 29762508, 2018). "Individuals with DICER1 also are at risk of developing cystic nephroma and multinodular goiters." (PMID 39963649, 2025). "The third patient (with a history of polycystic thyroid goiter in the female line in his mother’s family members) was simultaneously diagnosed with pleumopulmonary blastoma type II (PPB II) and pediatric cystic nephroma/nefroblastoma related to mutations in the DICER1 gene." (PMID 37761810, 2023). "The incidence of DICER1 mutations in cystic nephroma, for instance, approaches 70%." (PMID 31349569, 2019). "The frequency of DICER1 germline mutations in cystic nephroma patients was found to be 73.2%." (PMID 29762508, 2018). "Additionally, a nascent anaplastic sarcoma of the kidney (ASK) was reported within a cystic nephroma, associated with the presence of a germline DICER1 mutation, or alternatively due to a somatic mutation." (PMID 29762508, 2018). "In addition, pelvic ultrasounds every six to 12 months are recommended for females aged between eight to 40 years to monitor for possible growth of gynecologic or renal tumors, such as ovarian Sertoli-Leydig tumors and cystic nephromas (both associated with the DICER1 phenotype)." (PMID 39963649, 2025). "One child with DICER1 positivity had a history of cystic nephroma, and the other had a benign thyroid nodule." (PMID 40918549, 2025). "Pediatric cystic nephroma (PCN) is a similar lesion, epidemiologically restricted to children (usually males) below 2 years of age, and is molecularly characterized by a DICER1 mutation." (PMID 37444462, 2023). "Less commonly the DICER1 tumour spectrum includes: cystic nephroma (CN), and thyroid gland neoplasia, multinodular goitres [MNG], adenomas, or differentiated thyroid cancers." (PMID 26138824, 2015). "Genetic testing for DICER1 germline pathogenic variants must be offered in all patients with DICER1-related conditions, such as PPB, cystic nephroma, SLCT, cervical embryonal rhabdomyosarcoma, and pituitary and pineal blastoma, with or without positive family history." (PMID 40076617, 2025). "However, almost all patients afflicted by both cystic nephroma and PPB demonstrate DICER1 mutations." (PMID 31349569, 2019). "As opposed to adult cystic nephroma, paediatric cystic nephroma is now regarded a separate entity with specific DICER1 mutations." (PMID 28284198, 2017). "Mutations in DICER1 cause abnormalities in proteins that produce micro ribonucleic acids (RNAs) involved in cell proliferation, apoptosis, and cell differentiation, leading to the development of various malignant tumors such as PPB, rhabdomyosarcoma, cystic nephroma, and thyroid tumors." (PMID 37930461, 2023).